FKBP9P1 (FKBP prolyl isomerase 9 pseudogene 1)
Synonyms: MGC20531; formerly FKBP9L
Gene: Transcribed unprocessed pseudogene on chromosome 7 (55,682,652 to 55,713,252, reverse strand). Ensembl gene ENSG00000176826.
Diseases named in the same sentence as FKBP9P1 in open-access papers:
FKBP9P1 is named in the same sentence as 1 disease in open-access papers, as found by Europe PMC text mining. Sharing a sentence is not in itself a finding about the gene and the disease.
FKBP9P1 shares sentences with these, for which no sentence is quoted: tumor (1 paper).